KRAS (KRas proto-oncogene, GTPase)
Diseases named in the same sentence as KRAS in open-access papers (continued):
Sharing a sentence is not in itself a finding about the gene and the disease.
cancer (continued). "Second, our data showed ERK or STAT3 activation after PI3K inhibition alone in KRAS mutant cancer cell lines as a previous study showed that inhibition of mTORC1 induces RAS pathway as well." (PMID 22159814, 2012). "In other words, KRAS mutant cancers insensitive to single treatment of PI3K inhibitors seem to induce at least one signaling mediator in the alternate pathway, which contributes to resistance." (PMID 22159814, 2012). "Two of the KRAS-mutated and the single BRAF-mutated carcinoma showed loss of nuclear MLH-1 and PMS-2 immunostaining." (PMID 22808230, 2012). "Two recent studies demonstrate interesting relationships between cancer oncogenes (KRAS, BRAF and ErbB2), regulation of glucose transport and cell survival under conditions of stress." (PMID 21826239, 2011). "The true role of KRAS mutations in regards to EGFR therapy for PDAC is yet to be fully discovered and careful cancer-type distinction must be employed as there is little evidence demonstrating true prognostic power of this clinical marker." (PMID 21792199, 2011). "Cancer cells with wild type KRAS survived poorly in conditions of low glucose, but those that did survive upregulated GLUT1 and a small percentage acquired mutations in KRAS." (PMID 21826239, 2011). "LOH at Kras was not an artifact created by genetic engineering or unique to mice, because an increased frequency of LOH at KRAS was observed in human metastatic cell lines (80%) compared with primary cancer cell lines (37%)." (PMID 22113502, 2011). "Epidermal growth factor receptor (EGFR) and its downstream factors KRAS and BRAF are mutated in several types of cancer, affecting the clinical response to EGFR inhibitors." (PMID 21943394, 2011). "Cancer cells with mutant KRAS or BRAF have higher levels of GLUT1 RNA and protein expression and higher rates of glucose uptake and glycolysis which allows the cells to survive in conditions of low glucose." (PMID 21826239, 2011). "Increased LOH at KRAS was also observed in progression of human pancreatic primary tumors to metastases, again supporting a role for the KRAS gene in cancer metastasis." (PMID 22113502, 2011). "LOH at KRAS was confirmed by genomic sequencing of the KRAS gene in the cancer cell lines with LOH at chromosome 12p." (PMID 22113502, 2011). "Given the importance of KRAS activation for the selection of targeted cancer therapies, it is crucial that optimal methods are developed to measure the activation state of RAS in tumors." (PMID 20591134, 2010). "Global gene expression analyses of these cell lines reveal that HIF-1α and HIF-2α work together to modulate cancer metabolism and regulate genes signature overlapping with oncogenic KRAS." (PMID 21073737, 2010). "Using data in the Catalog of Somatic Mutations in Cancer (COSMIC) database, we have demonstrated that our method detects well-known clusters of activating mutations in KRAS, BRAF, PI3K, and β-catenin." (PMID 20053295, 2010). "KRAS and BRAF mutational frequencies were 19% and 43% in proximal carcinomas and 25% and 17% in rectal/sigmoid carcinomas, respectively." (PMID 20979647, 2010). "We robustly detected cancer gene mutations that direct clinical use and predict resistance to existing agents such as tyrosine kinase inhibitors (e.g., EGFR and KRAS mutations)." (PMID 19924296, 2009). "Further, this data suggest that the RAF-MEK-ERK cascade is predominantly engaged by KRAS in these cancer cells for growth and proliferation." (PMID 19492075, 2009). "The three RAS oncogenes (HRAS, KRAS and NRAS) are mutationally activated in ~30% of all cancers and are implicated in promoting multiple aspects of the malignant cancer phenotype." (PMID 19682393, 2009). "KRAS2 (KRAS) is a signal transduction GTPase, turned permanently on by somatic mutation in many cancers, including breast." (PMID 19327144, 2009).
cancer (continued). "Oncogenic mutations in the RAS family of small GTPases, KRAS, HRAS and NRAS, occur in approximately a third of all human cancers." (PMID 19492075, 2009). "According to the Catalogue of Somatic Mutations in Cancer (COSMIC) database from the Sanger Institute, KRAS mutations occur in only approximately 3% of all cancers of the oral cavity, pharynx, or larynx while HRAS mutations occur in 10% of these cancers." (PMID 19636423, 2009). "Taken together, these results suggested that the amplification of KRAS is involved in the promotion of cancer cell growth through the activation of the p44/42 MAP kinase pathway, and in part through activation of the AKT pathway." (PMID 19545448, 2009). "Previous reports and Cancer Genome Project by Sanger Institute have extensively characterised LKB1 mutations in NSCLC cell lines with KRAS and BRAF mutations, but LKB1 status of EGFR mutant NSCLC cell lines has not been extensively analysed." (PMID 18594528, 2008). "There remains an unmet need for effective drugs targeting KRAS-driven cancers." (PMID 42233520, 2026). "We found that KRAS E4 PSI values were broadly distributed across cancer tissues." (PMID 41368203, 2026). "Targeting the glutamine transporter SLC7A5 suppresses the proliferation of KRAS-mutant cancers." (PMID 41362725, 2026). "We speculate that the in vitro culture conditions of cancer cell lines may promote strong E4 exclusion in KRAS mRNA." (PMID 41368203, 2026). "Attempts of gene editing in KRAS have been reported in cancer studies using Clustered Regularly Interspaced Short Palindromic Repeats (CRISPR)/CRISPR associated protein 9 (Cas9) technology to generate double-strand breaks and disrupt variant KRAS alleles." (PMID 41272322, 2026). "This line of investigation may provide novel strategies for precision therapy in KRAS-driven cancers." (PMID 41513632, 2026). "Based on these profiles, we hypothesized that RBM47 and PTBP1 regulate the alternative splicing of KRAS E4, consistent with the positive correlations observed in TCGA cancer tissues." (PMID 41368203, 2026). "We first analyzed the global alternative splicing patterns of KRAS E4 in cancer tissues." (PMID 41368203, 2026). "We classified patients with cancer by the presence or absence of hotspot mutations in the KRAS gene and estimated the mRNA expression patterns of KRAS splicing variants." (PMID 41368203, 2026). "Other research found that the combination of type II RAF inhibitors with MEK inhibitors could overcome acquired resistance in KRAS-mutant cancers." (PMID 41362725, 2026). "Across pan-cancer analyses, while KEAP1 mutations were enriched in KRAS G12C tumors (15.38% vs. 4.61% in non-G12C), this pattern was less pronounced in NSCLC-specific contexts, likely attributable to overlapping mutational landscapes and tissue-specific selection pressures." (PMID 41541668, 2026). "Overall, our findings indicate that RBM47 and PTBP1 regulate the alternative splicing of KRAS E4 in human cancers, and that the resulting KRAS4A splicing isoforms may promote cancer cell proliferation and metastasis." (PMID 41368203, 2026). "We next analyzed the role of KRAS splicing isoforms in cancer cell metastasis." (PMID 41368203, 2026). "Additionally, we identified that the mRNA expression of splicing factors RBM47 and PTBP1 positively correlates with KRAS E4 inclusion rates in cancer tissues and confirmed their roles in enhancing E4 inclusion in KRAS mRNA." (PMID 41368203, 2026). "Notably, all four KRAS missense mutations have reported resistance to EGFR inhibitors (cetuximab, panitumumab) and HER2 inhibitors (tucatinib + trastuzumab) for various cancers." (PMID 41009531, 2025). "Moreover, we demonstrated that SIAIS562055 alone induced robust antitumor efficacy and exhibited synergistic activity when combined with KRAS inhibitors in KRAS-mutant cancers, including those with acquired resistance to KRAS inhibitors." (PMID 39437162, 2025).
cancer (continued). "Moreover, a next-generation FTI, KO-2806, has re-opened a possible indication in KRAS-mutant cancers." (PMID 39995872, 2025). "However, only one of 18 patients enrolled had PC, so there is still a need for further investigation of KRAS G12D inhibitors in this type of cancer." (PMID 40805153, 2025). "KRAS occupies a special position in cancer research history." (PMID 41049269, 2025). "These strategies can also be combined, as bispecific antibodies that cross‐link HLA‐A*02:01 presenting ARS1620‐modified epitope to CD3+ T cells could induce cancer cell killing even of cancer cells resistant to direct KRAS G12C inhibition." (PMID 39609891, 2025). "Notably, BI-346 reduces feedback reactivation caused by MEK inhibitors, thereby increasing the sensitivity of KRAS dependent cancers to MEK inhibition." (PMID 40362343, 2025). "They found that shortly after treatment, some cancer cells enter a quiescent state with low KRAS activity, while others bypass inhibition by producing newly synthesised KRASG12C, which is maintained in an active, drug‐insensitive state via EGFR‐ and AURKA‐driven signalling." (PMID 41025426, 2025). "Many cancers are characterized by the dysregulation of KRAS signaling." (PMID 41514544, 2025). "Furthermore, KRASG12C inhibitors cover only a small fraction of all KRAS mutants, whereas several KRASG12D inhibitors for KRAS mutation–related cancers are currently undergoing clinical trials." (PMID 40091835, 2025). "Patients with KRAS mutant cancers are shown to have microbiomes with a higher abundance of Roseburia, Parabacteroides, Staphylococcus, and Staphylococcaceae than patients with non-mutant KRAS cancers, suggesting that interplay between microbial and mutational profiles influences cancer development." (PMID 40075661, 2025). "Thus, given the high proteasome capacity that is characteristic of KRAS-mutant tumors, there is an urgent need to develop selective and low-toxicity proteasome inhibitors for optimal therapy in KRAS-mutant cancers." (PMID 40091835, 2025). "This evidence indicates that the proteasome is a potential drug target in KRAS-mutant cancer cells." (PMID 40091835, 2025). "This synergy could overcome the intrinsic resistance observed in many KRAS-mutant cancers, which aligns with recent clinical investigations that suggest that metabolic interventions may increase the efficacy of targeted therapies." (PMID 40437561, 2025). "The KRAS signaling pathway is well known for promoting cancer cell survival and immune evasion in tumors, and some studies suggest that it may also support repopulation under certain conditions." (PMID 40312750, 2025). "Consequently, current cancer immunotherapies have failed in patients with EGFR mutations, while patients with KRAS mutations have more favorable outcomes." (PMID 40524071, 2025). "For instance, KRAS-driven tumors (a common scenario in MOC) have been shown to depend on certain cell-cycle regulators for survival, suggesting that inhibiting such a partner in KRAS-mutant MOCs could selectively eliminate the cancer cells." (PMID 40862711, 2025). "The aim of this study is to determine how sotorasib could radiosensitize cancer cells and how combining C-ion irradiation and sotorasib could eradicate CSC in the KRAS G12C mutated cell line (H358 cells) in vitro." (PMID 40361506, 2025). "Taken together, we propose that, in addition to inhibiting mutant KRAS, the anti-cancer effect of G12Ci drugs is also mediated by the electrophile-mediated induction of NRF2, which results in induction of NISP expression, and the concomitant promotion of the anti-cancer immune response." (PMID 40890297, 2025). "In addition, it has been shown that SHP2 inhibitors effectively overcome adaptive resistance to MEK inhibitors in KRAS mutant cancers." (PMID 40731832, 2025). "Additionally, these genes were also enriched in cancer-related pathways, including glycolysis, hypoxia, adipogenesis, myogenesis, KRAS signaling, and EMT." (PMID 40303305, 2025).
cancer (continued). "Emerging immunotherapy strategies, such as oncolytic virus therapy (OVT), adoptive cell transfer therapy (ACT), and cancer vaccines—including innovative KRAS mutant peptide-based vaccines in adjuvant settings—show promising potential across various tumor types, including PDAC." (PMID 40002184, 2025). "KRas-G12C-expressing cancer cells also express wild-type (WT) HRas and NRas (H/NRas), thus WT Ras may have a compensatory role during mutant KRas inhibition." (PMID 39103633, 2025). "Notably, Liu's group demonstrated that combining BSO with the NADPH oxidase inhibitor DPI effectively kills cancer cells with HRAS G12V and KRAS mutations, suggesting a promising dual-targeting strategy for RAS-driven cancers." (PMID 40403492, 2025). "Glecirasib could also potently inhibit cell viability of KRAS p.G12C–carrying cancer cell lines, such as NCI-H1373, NCI-H385, and MIA PaCa-2, with a low median IC50 value of 11.8 nmol/L (n = 7)." (PMID 40304209, 2025). "As a protein with increased binding in KRAS G12C/D/V mutation groups, LAMTOR1 may emerge as a potential therapeutic target for cancer treatment." (PMID 40427667, 2025). "We think that these oncogenic features may confer a growth advantage to KRAS-mutant cancer cells under 3D culture conditions, especially in our system, where additional growth factors such as Wnt3a, R-spondin-1, and Noggin were excluded." (PMID 40462147, 2025). "In KRAS mutant cancers, the mitogen-activated protein kinase (MAPK) pathway plays an active role." (PMID 40731832, 2025). "Moreover, studies have shown that mutant KRAS alters the basal metabolism of cancer cells, increasing glutamine utilization to support proliferation." (PMID 40443528, 2025). "Similar to key mutations in oncoproteins (G12 in KRAS, V600 in BRAF, or T41 in β-catenin), we investigated whether mutations at T980 occur in FASN across various cancers." (PMID 40684943, 2025). "Oncogene addiction has been documented for KRAS mutants, whereby adenocarcinoma cell lines harboring KRAS mutations have been classified as KRAS-dependent or KRAS-independent.This study defines the relationship between KRAS addiction, TIMP-1 expression, and EMT in cancer progression." (PMID 41002380, 2025). "CodeBreaK 101 (NCT04185883) is an ongoing phase 1 trial exploring sotorasib monotherapy and in combination with other anti-cancer therapies, including anti-EGFR agents (panitumumab), MEK inhibitors, and ICIs, in advanced solid tumors harboring the KRAS G12C mutation." (PMID 40361439, 2025). "Taken together, these data suggest that SIAIS562055-induced degradation of SOS1 leads to the suppression of downstream signaling, which effectively inhibits the proliferation of KRAS-mutant cancer cells and shows synergistic effects when combined with KRAS inhibitors." (PMID 39437162, 2025). "Tipifarnib, in particular, has gained renewed interest as a potential treatment for HRAS-mutant cancers and as part of combination therapy with KRAS G12C inhibitors, such as sotorasib, demonstrating synergistic effects in preclinical lung adenocarcinoma models." (PMID 40597785, 2025). "While RASD1 expression generally remains low in most cancers compared to normal tissues, we observed the opposite in THYM, a cancer with a low incidence of KRAS mutations, and UCEC, a cancer in which patients with KRAS mutations exhibit a more favorable prognosis." (PMID 40362656, 2025). "Attempts have been made to use RAS(ON) inhibitors for the treatment of KRAS G12D-positive cancers." (PMID 40597785, 2025). "Notably, although initial FTI treatments in KRAS-mutant cancers were unsuccessful, renewed interest in selective FTIs and rational combination therapies suggests potential utility in specific contexts." (PMID 41514544, 2025). "Additionally, understanding the heterogeneity of the immune microenvironment in KRAS-mutant cancers presents challenges but offers opportunities for precision treatment." (PMID 40611261, 2025).
cancer (continued). "BRAFV600E mutations were overrepresented in IDH‐mutant cancers (OR = 4.09; 95% CI = 2.07–8.06; p = 1.9 × 10−4), while KRAS driver mutations were not (OR = 1.17; 95% CI = 0.61–2.26; p = 0.73)." (PMID 40545636, 2025). "Lastly, extending these studies to other KRAS-driven cancers may reveal whether APE1 dependence is a more widespread oncogenic vulnerability." (PMID 41510226, 2025). "Although these initial findings sparked excitement in the KRAS-mutant cancer field, less than 2% of patients with PDAC harbor KRASG12C mutations, limiting how beneficial this therapeutic avenue might be." (PMID 40829181, 2025). "Consequently, KRAS becomes constitutively activated and persistently stimulates downstream signaling pathways driving cancer hallmarks." (PMID 40002297, 2025). "This has rendered KRAS one of the most notorious ‘undruggable’ targets in cancer therapy." (PMID 40517320, 2025). "Therefore, the identification of TCRs targeting mutant KRAS will facilitate the development of TCR-based therapies against mutant KRAS cancers." (PMID 39846249, 2025). "Glecirasib could robustly inhibit ERK phosphorylation in cancer cells carrying KRAS p.G12C, with a median IC50 value of 10.9 nmol/L (n = 7)." (PMID 40304209, 2025). "It is worth mentioning that this study shows that Melittin can boost the anti-cancer effects of Erlotinib in NSCLC, potentially by affecting the JAK2–JAK3 pathway, which could be helpful even in KRAS-mutant cancers." (PMID 40243485, 2025). "Furthermore, the KRAS signaling pathway, IL6/JAK/STAT3 pathway, and IL-2/STAT5 pathway were strongly linked to STX7 expression in cancer." (PMID 40999361, 2025). "KRAS WT–amplified cancers represent a considerable (∼7%) fraction of KRAS-driven cancers, with an incidence of 9,000 patients every year in the United States, based on data across seven major cancer types." (PMID 39711431, 2025). "However, induction of BIM by MEK or KRASG12C inhibition alone is often insufficient to induce apoptosis in KRAS-mutant cancer cells because BIM is bound and neutralized by pro-survival BCL-2 family proteins such as BCLX-XL or MCL-1." (PMID 40316540, 2025). "Somatic mutations in the KRAS, HRAS, and NRAS genes are often presented in different cancers." (PMID 41438146, 2025). "This suggests that the Do‐Cy nanocomplex could potentially exhibit selective targeting in other KRAS‐mutant cancers." (PMID 39951277, 2025). "Indeed, all the genes were overexpressed in the CRC mutant compared to the KRAS WT cancer cell lines, except for DKK1 and ECM1." (PMID 40013338, 2025). "Moreover, we observed a strong expression of REGγ in KRAS-mutant (KRAS-MUT) cancers, which was supported by data from The Cancer Genome Atlas (TCGA) datasets." (PMID 40091835, 2025). "Importantly, as these cell lines do not express KRASG12C, these results show that part of the chemokine-induced anti-cancer immune response which is mediated by G12Ci drugs can be modulated independently of KRAS inactivation." (PMID 40890297, 2025). "Such investigations may reveal novel combination strategies that could improve the therapeutic efficacy of treatments for KRAS‐mutant cancers." (PMID 40596709, 2025). "Besides PD-1/L1 single-agent immunotherapy, other immunomodulatory treatments for KRAS-mutant cancers are undergoing clinical trials." (PMID 41184283, 2025). "In addition to repressing oncogenic KRAS signaling, the therapeutic efficacy of G12Ci is also mediated through the upregulation of the anti-cancer immune response." (PMID 40890297, 2025). "Furthermore, machine‐learning algorithms applied to pan‐KRASG12C‐ and pan‐KRAS‐mutant cancer cell lines confirmed the superior predictive performance of subtype‐derived signatures for G12Ci sensitivity." (PMID 41025426, 2025).